AR (androgen receptor)
Diseases named in the same sentence as AR in open-access papers (continued):
Sharing a sentence is not in itself a finding about the gene and the disease.
tumor (continued). "Conversely, TRAMP C1 tumours had notably less AR staining likely due to fewer glandular structures, with some tumours lacking AR expression entirely." (PMID 33003551, 2020). "Taken together with the previous in vitro results, the effects of menin inhibition seen with our tool inhibitor BAY-155 on AR and ER pathways are minor and not robust enough to translate into a significant anti-tumor effect in our models." (PMID 31947537, 2020). "In our study, Cath-D expression in tumor cells was more frequently detected in AR+ than AR-TNBC, and 62.7% of non-metastatic TNBC harbored AR/Cath-D co-expression." (PMID 32429078, 2020). "Here we report for the first time that combined AR and HIF1a signaling in vivo promotes tumor growth and demonstrate the capacity of HIF1a to promote tumor growth in the absence of endogenous androgen in vivo." (PMID 32450824, 2020). "Although the precise mechanisms remain unclear, the AR-positive tumor cell subpopulation can support the growth of a cancer stem cell (CSC)-like cells, which promote chemotherapy resistance and tumor recurrence." (PMID 33213491, 2020). "The analysis presented in this study underscores the importance of AR expression in the primary tumor as a robust and independent biomarker in non-metastatic TNBC and provides prognostic information in patients with LN metastasis." (PMID 32850312, 2020). "These isoforms can drive an AR transcriptional program even in the absence of androgen signaling, resulting in androgen independent tumor growth." (PMID 33062889, 2020). "In multivariate analyses, higher tumor size, no adjuvant chemotherapy and AR/Cath-D co-expression were independent prognostic factors of worse overall survival." (PMID 32429078, 2020). "The results from our work suggest that AR agonists and antagonists may dysregulate ASE within the pre-mRNA of genes that regulate tumor biology." (PMID 32820253, 2020). "In the present study, the clinical importance of ZEB1 expression and its correlation with AR expression were assessed in GC using tumor and adjacent non-tumor tissues from GC patients, normal gastric tissues from normal cases and two GC cell lines." (PMID 32153739, 2020). "GSEA results and follow-up studies on the expression and activity of AR and target genes shown herein provide evidence that the tumor suppressor actions of ERβ in PCa are due to its negative regulation of AR signaling." (PMID 32413024, 2020). "ChIP revealed that NCL binds to the region of the AR promoter containing the G4-element in androgen-dependent (LNCaP/VCaP) and CRPC (22Rv1) AR-expressing tumor cells, but not in AR-negative tumor cells (PC3)." (PMID 32477465, 2020). "A lack of AR signaling in the bone marrow prevents the maturation of neutrophils and impedes homing to tumor-bearing lungs." (PMID 32235862, 2020). "Mulholland and Carver showed that both PI3K and AR pathway inhibition by AKT inhibitor and deprivation of androgen could head remarkable tumor reduction compared to inhibition of the single pathway." (PMID 32972001, 2020). "In contrast, in ERα-negative tumors, AR binds to androgen-responsive elements (EREs), leading to cell proliferation and tumor growth." (PMID 31952272, 2020). "The compounds did not impede nuclear localization of the AR, but they blocked interactions with chromatin and demonstrated the inhibition of gene expression and tumor volume in mouse xenografts." (PMID 33076388, 2020). "The AR status of the tumour had no impact on either overall (p = 0.293) or disease-free survival (p = 0.826) when the tumours were categorized by molecular subgroup." (PMID 32928183, 2020). "SRD5A1 expression levels and AR pathway activity scores were not significantly different between primary tumor tissue, lymph node metastatic tissue and distant metastatic tissue." (PMID 31745978, 2020).
tumor (continued). "In vivo, it prevents tumor growth in AR-expressing xenograft models with limited toxicities.The most potent stereoisomer, EPI-002, was developed into a prodrug, EPI-506, which was the first AR NTD inhibitor tested in a Phase 1 study in men with CRPC." (PMID 33076388, 2020). "Δ4-Abiraterone has anti-tumor activity since it inhibits P450c17, HSD3B1, and is an antagonist of the AR, leading to the concept that abiraterone acetate may be a pro-drug and that Δ4-abiraterone is the active metabolite." (PMID 35582223, 2020). "Concerning AR IHC staining, we identified 77 (51%) tumor specimens with positive AR staining and 74 (49%) cases with a negative AR staining." (PMID 33208857, 2020). "In the present cohort, the expression of AR per se in the tumor cells did not modify patient survival." (PMID 32718331, 2020). "PD-L1 expression on tumor cells and PD-1 expression on TILs were not different in tumor co-expressing or not AR and Cath-D, in our population." (PMID 32429078, 2020). "Such a phenotype comprising modifications such as AR downregulation (low or absent AR protein expression) and the acquisition of tumor cells with stem-like habits is notoriously correlated with very poor survival outcomes." (PMID 33321757, 2020). "One of these mechanisms involves the switching of tumor cells to a neuroendocrine differentiation and/or growth independent of AR signaling." (PMID 32645914, 2020). "In this context, AR negatively regulates expression of ZBTB46, a tumor promoter through miR-1129." (PMID 33062889, 2020). "Finally, in AR-positive CWR22υ1 PCa cell-bearing mice, fisetin inhibited tumor growth and decreased PSA serum levels, suggesting that this compound is able to suppress AR activity also in vivo." (PMID 32085497, 2020). "In the tumor xenografts, IHC staining demonstrated enzalutamide treatment reduced the expression of both KLF5 and AR, which is consistent with in vitro findings, and KLF5 silencing also downregulated AR expression." (PMID 32245249, 2020). "There were no changes in AR expression in tumor tissues of patients with metastases compared with tumor tissues of patients without lymph node metastases in other subtypes of BC." (PMID 32373367, 2020). "There are several emerging therapies and repurposed drugs targeting tumor-driving signaling pathways in TNBC, including epidermal growth factor (EGFR/HER1) antibodies, PI3K/AKT/mTOR, and angiogenesis inhibitors, androgen receptor (AR) antagonists, and estrogen receptor beta (ERβ) agonists." (PMID 32846967, 2020). "For KDM5D encoded on the X-chromosome, a direct interaction with the androgen receptor in the tumor cell nucleus could be demonstrated, and a reduction in the expression of KDM5D leads to disruption of the androgen receptor pathway." (PMID 32629877, 2020). "In summary, we identified miR-9-5p as a tumor suppressor gene in BC, regardless of ER status, capable of down-regulating AR in BC cells and to inhibit AR downstream signaling even in presence of androgen agonists." (PMID 33282861, 2020). "Whilst this requires further investigation, there is also scope to investigate the utility of IKBKE targeting therapeutics in highly aggressive AR negative tumours." (PMID 32324216, 2020). "In addition, JQ1 showed significant anti-tumor activity in vivo in TNBC xenograft mouse models as a monotherapy and in combination with anti-AR therapy." (PMID 31527644, 2019). "Another possible explanation for castration-resistance acquisition is the presence of tumor cells that can activate down-stream transcription without the presence of the AR, such as GR signalling as an alternate pathway." (PMID 31727962, 2019). "Overlap between ER+ BRCA/AR+ TNBC tumor and normal samples is absent in PC2, as opposed to that observed for PRAD tumor and normal samples, showing overlap in both PCs." (PMID 31238876, 2019).
tumor (continued). "This leads to emergence of AR-null or neuroendocrine-like PCas that are very difficult to treat due to the lack of endocrine targets left in the tumor, and chemotherapy becomes the last alternative to help the patient." (PMID 31142021, 2019). "Lentiviral-mediated LRIG1 overexpression in AR− PCa cells, Du145 and PPC-1, inhibited tumor incidence and/or tumor growth (weight) in NOD/SCID mice, which was associated with decreased cell proliferation (Ki-67+ cells) and slightly increased cell death (cleaved lamin A+ cells) in endpoint tumors." (PMID 31792211, 2019). "The role of the AR in BC has not yet been completely elucidated and seems to depend on tumour subtype." (PMID 31718606, 2019). "In the Kaplan-Meier analysis in the monotherapy population (n = 1753), BCFI was better for those assigned to letrozole than tamoxifen, regardless of tumor AR expression (AR+ p = 0.02 from log-rank test; AR− p = 0.04)." (PMID 30795773, 2019). "Our team has reported that the vasopressin analog desmopressin, a selective agonist for the vasopressin receptor 2 (AVPR2), significantly reduced tumor cell growth and migration in AR-negative CRPC." (PMID 31998646, 2019). "We further show that 1) AR directly transactivates LRIG1 through binding to several AR-binding sites in LRIG1 locus, and 2) LRIG1 dampens ERBB expression in a cell type-dependent manner and inhibits ERBB2-driven tumor growth." (PMID 31792211, 2019). "Despite the lack of requirement of CRPC tumours for circulating androgens, it is widely accepted that AR signalling is still driving their growth." (PMID 31043708, 2019). "Finally, the two CR tumor cell lines, DU145 and PC3, were established from metastatic deposits (central nervous system and bone/lumbar spine, respectively), lack the AR and are androgen-independent." (PMID 31675377, 2019). "Detection in patients’ circulating tumor cells (CTCs) of ARV7, a splicing variant of AR lacking the ligand-binding domain, showed a link with treatment failure." (PMID 31337040, 2019). "ChIP sequencing data (GSE56288) revealed recruitment of AR to the vicinity of the HOTPAM9 genomic regions in the tumor tissues but not in normal prostates." (PMID 31273254, 2019). "Gleason scores, basal PSA levels, and previous local treatment on the primary tumor were associated with CTC detection and AR expression, but not with the expression of the variant ARV7." (PMID 31337040, 2019). "Androgen resistance is not related only to androgen receptor reactivation, but also to mechanisms related to tumor heterogeneity." (PMID 31366128, 2019). "Results about the tumor suppressive role of let-7a were confirmed also in AR+/ER+ BC cells, where DHT stimulation led to an AR translocation to the nucleus with transcriptional upregulation of let-7a, decreased cell proliferation, self-renewal capacities, invasion and migration." (PMID 30941159, 2019). "In vivo androgen receptor-shRNA-decorated NPs could significantly suppress tumor growth and prolong the survival of HIPC tumor-bearing mice." (PMID 30943985, 2019). "Taken together, these data confirm that AR-modulatory miRs and their biologically relevant PC targets are altered in cancer vs normal tissue, correlate with disease progression and AR activity, and are altered in response to hormone therapy in a CRPC patient tumour." (PMID 31043708, 2019). "Transcriptome profiling provided evidence that reduced, but persistent AR activity in residual tumor foci, with no increase of neuroendocrine differentiation." (PMID 31366128, 2019).
tumor (continued). "Importantly, we also demonstrated that sGC inhibitor treatment repressed tumor growth in TMPRSS2-ERG-positive PCa xenograft models and can act in synergy with a potent AR antagonist, enzalutamide." (PMID 30718921, 2019). "This contributes to some imbalances in tumor characteristics between the populations with and without assessable AR expression." (PMID 30795773, 2019). "In addition, the tumor suppressor miR-486 and miR-367-3p have been shown to promote sorafenib sensitivity by inhibiting CITRON, claudin 10 (CLDN10) and androgen receptor (AR)." (PMID 31651347, 2019). "AR ChIP‐seq results from our patient samples confirm the utility of this operational definition of the AMS, as using their T‐ARBSs and N‐ARBSs clearly segregated our samples into normal or tumor by unsupervised hierarchical clustering." (PMID 31520575, 2019). "Since the expression of PSA is mediated by the transcriptional activity of nuclear AR, a higher initial PSA value may represent a higher basal AR activity inside the tumor microenvironment." (PMID 30978937, 2019). "Overriding this resistance requires understanding of the driving mechanisms of the tumor microenvironment, not just the androgen receptor (AR)-signaling cascade, that facilitate therapeutic resistance in order to identify new drug targets." (PMID 29562686, 2018). "Finally, we found that compared with the inhibition of AR expression alone, simultaneous inhibition of AR and PDEF expression further suppressed tumour proliferation both in vitro and in vivo." (PMID 30217192, 2018). "Their aberrant expression in malignant SGTs was sporadically reported in MEC, a very poor prognosis tumor, and never reported for oncocytic carcinoma, suggesting the use of AR antagonists in therapeutic strategies for these patients." (PMID 29385707, 2018). "ERα and AR show clustering within patient rather than between factors, indicating a stronger correlation between factors within the same tumor as compared to the same factor between tumors." (PMID 29396493, 2018). "In luminal androgen receptor (AR) tumours, FOXA1 may direct AR to sites occupied by ER in luminal tumours, thus stimulating proliferation." (PMID 29880907, 2018). "These cells do not exhibit AR to ARE binding or AR nuclear translocation yet targeting AR decreases tumor migration and proliferation." (PMID 30416486, 2018). "Emerging studies have shown that the expression of AR splice variants (ARv) lacking ligand-binding domain is associated with castrate-resistant prostate cancer (CRPC) and higher risk of tumor metastasis and recurrence." (PMID 30450161, 2018). "Although the requirement for androgen is no longer necessary in CRPR, AR can still potentiate tumor growth and survival, and appears to be the principal accomplice in progression towards complete androgen-independence." (PMID 29464071, 2018). "Cumulative incidence analysis showed that AR-negative patients within all subtypes had shorter times to progression than those for AR-positive patients (p<0.05 regardless of tumor subtype." (PMID 29912871, 2018). "Importantly, our studies further demonstrate that targeting BMI1 by PTC209 significantly inhibits CRPC tumor growth, and combinational targeting of BMI1 and AR achieves better efficacy than single agents alone." (PMID 29402932, 2018). "In contrast, AR deletion did not affect tumor initiation following combined deletion of Pten and activation of the oncogenic KrasG12D allele." (PMID 29334357, 2018). "We show here that unsupervised patient classification based on genome-wide profiles for AR, H3K27ac, and H3K27me3 (but not H3K4me3) groups patients in strong accordance to RNA-seq-based tumor profiling." (PMID 30464211, 2018). "Next, we investigated whether simultaneous inhibition of AR and PDEF expression further suppressed tumour proliferation compared with the inhibition of AR alone." (PMID 30217192, 2018).
tumor (continued). "In this category, tumor cells proliferate under ADT without activation of the AR or expression of AR target genes." (PMID 30248934, 2018). "AR status was independent of ER-or PR expression status, and AA tumor had highly significant differences in AR status compared to White patients (p<0.001)." (PMID 29912871, 2018). "As expected, the efficacy of the CpdA was more significant in the GR-positive/AR-positive cells than in the GR-positive/AR-negative or the GR-negative/AR-positive cells, suggesting its anti-tumor activity via both the GR and the AR pathways." (PMID 30518063, 2018). "Another mechanism includes activation of the gastrointestinal (GI) lineage transcriptional program in CRPC, in which the resistant tumor cells utilize two hepatocyte nuclear factors (HNF1A and HNF4G), that drive an alternate lineage-specific program due to suppression of AR signaling." (PMID 29600194, 2018). "Coexpression of Forkhead box A1 (FOXA1) with androgen receptor (AR) could be used as a biomarker for the identification of subtypes of TNBC and promotes tumor cell proliferation." (PMID 30175120, 2018). "In almost congruent concentration ranges the 3β-isoform of adiol also elicited decreased proliferation of PCa-cells with AR-aberrations but not in AR-negative PC-3 tumour cells and non-neoplastic AR-positive BPH-1 cells." (PMID 29682196, 2018). "Compared with the paired non-tumor liver tissues, significant up-regulation of CCRK, p-GSK3βSer9/GSK3β, p-mTORSer2448/mTOR, p-4E-BP1Thr37/46/4E-BP1, p-S6KThr389/S6K, mSREBP1, G-CSF, p-STAT3Tyr705/STAT3, and AR were detected in HCC tissues (p < 0.05)." (PMID 30523261, 2018). "This wide range in reported incidence of AR expression in TNBC can be attributed, at least in part, to differences in immunoreactivity threshold used to define immunopositivity, in tissue fixation, in AR analysis, and/or in tumor heterogeneity." (PMID 29883487, 2018). "Moreover, FGF and MAPK pathways have been reported to drive tumor progression, whereby activating the FGF pathway can bypass AR signaling and promote ARPI resistance in tumor cells." (PMID 29666783, 2018). "AR and LSD1 colocalize on promoters and stimulate H3K9 demethylation without altering the H3K4 methylation status and promote ligand dependent transcription of AR target genes resulting in enhanced tumor cell growth." (PMID 30344952, 2018). "AR and PDEF were more often co-expressed, with 55 (55%) cases having AR+PDEF+ tumours." (PMID 30217192, 2018). "The implications of our findings are far-reaching as GR is emerging as a key driver of PCa tumor aggressiveness, especially in the absence of AR signaling." (PMID 30305646, 2018). "Their findings show, that ID4 regulates the AR activity by interaction with FKBP52, whereas in absence of ID4 FKBP52 potentiates AR signaling and leads to increased proliferation and tumor growth." (PMID 30568592, 2018). "The study also provides a clue about the communication between the EGFR/AR axis and MMP-9, which might be a crucial component of tumor dissemination and establishment at the metastatic sites." (PMID 30134822, 2018). "In the TCGA dataset, we found that AA women with either non-TNBC or TNBC tumor types had lower AR gene expression compared to their White counterparts." (PMID 29912871, 2018). "In that study, several tumors initially diagnosed as AR-negative SDCs were reclassified as other tumor entities after a second evaluation by salivary pathologists." (PMID 28208703, 2017). "In patients with ER-positive tumors, multivariate analysis revealed that AR(-)/FOXA1(-) tumors were independently poor prognostic factors for DFS and OS when age at diagnosis, tumor and node stage, histologic grade, HER2, Ki-67, and use of chemotherapy and endocrine therapy were adjusted." (PMID 29137314, 2017). "We observed that AR expression did not vary significantly across the PCa grades or the tumor stages T2 and T3." (PMID 28235401, 2017).